C2orf78 (chromosome 2 open reading frame 78)
Synonyms: FLJ43987; hCG1989538; COG5373
Tractability: No criterion of Open Targets' tractability assessment is met for any kind of drug.
Gene: Protein-coding gene on chromosome 2 (73,784,183 to 73,817,148, forward strand). Ensembl gene ENSG00000187833.
Subcellular location (Human Protein Atlas): Nucleoplasm
Genetic constraint (gnomAD): Loss-of-function variants: 11 observed, 20.39 expected, observed/expected ratio (o/e) 0.54, 90% interval 0.34 to 0.89. The upper end of that interval is the gene's LOEUF score, 0.89, which puts it in group 3 of 6, group 1 being the genes least tolerant of losing a copy. Missense variants: 1,032 observed, 1,114.6 expected, observed/expected ratio (o/e) 0.93, 90% interval 0.88 to 0.98. Synonymous variants: 394 observed, 422.26 expected, observed/expected ratio (o/e) 0.93, 90% interval 0.86 to 1.01.
Homologues: Orthologues: chimpanzee C2AH2orf78 (94% identical), macaque C13H2orf78 (93% identical), dog C2orf78 (68% identical), rat C1h2orf78 (47% identical), mouse Gm5114 (45% identical), mouse Gm5591 (44% identical), mouse Gm5592 (44% identical), rat C1h2orf78l1 (42% identical), rat 4930433I11Rikl (38% identical), mouse 4930433I11Rik (37% identical), mouse Gm4884 (34% identical).
Diseases named in the same sentence as C2orf78 in open-access papers:
C2orf78 is named in the same sentence as 4 diseases in open-access papers, as found by Europe PMC text mining. Sharing a sentence is not in itself a finding about the gene and the disease. The quoted sentences say what the papers report.
male infertility (1 paper, 2025). The inability of the male to effect fertilization of an ovum after a specified period of unprotected intercourse. "Most of the top 60 genes are poorly characterized, and several have been recently linked to human male infertility, including C2orf78, POTEJ, and PROK2." (PMID 41282076, 2025).
C2orf78 also shares sentences with these, for which no sentence is quoted: cancer (1 paper); diabetes (1); Obesity (1).